MBLAC2 (metallo-beta-lactamase domain containing 2)
Description:
Acyl-CoA thioesterases are a group of enzymes that catalyze the hydrolysis of acyl-CoAs to the free fatty acid and coenzyme A (CoASH), providing the potential to regulate intracellular levels of acyl-CoAs, free fatty acids and CoASH. Has an acyl-CoA thioesterase activity towards the long chain fatty acyl-CoA thioester palmitoyl-CoA (hexadecanoyl-CoA; C16:0-CoA). Displays a substrate preference for fatty acyl-CoAs with chain-lengths C12-C18. Possesses beta-lactamase activity, catalyzing the hydrolysis of penicillin G and nitrocefin. Exhibits no activity towards other beta-lactam antibiotic classes including cephalosporins (cefotaxime) and carbapenems (imipenem).
Synonyms: DKFZp686P15118; MGC46734
Tractability: Antibody: UniProt places it where antibodies can reach, with high confidence; its Gene Ontology location is reachable by antibodies, with high confidence. PROTAC: ubiquitination databases record sites on it; its protein half-life has been measured.
Gene: Protein-coding gene on chromosome 5 (90,458,209 to 90,474,771, reverse strand). Ensembl gene ENSG00000176055.
Subcellular location: Endoplasmic reticulum membrane; Cell membrane
Subcellular location (Human Protein Atlas): Mitochondria; Nucleoplasm
Gene Ontology:
Molecular function: beta-lactamase activity; long-chain fatty acyl-CoA hydrolase activity; protein binding; medium-chain fatty acyl-CoA hydrolase activity
Cellular component: endoplasmic reticulum membrane; extracellular exosome; mitochondrion; plasma membrane
Genetic constraint (gnomAD): Loss-of-function variants: 24 observed, 22 expected, observed/expected ratio (o/e) 1.09, 90% interval 0.79 to 1.53. The upper end of that interval is the gene's LOEUF score, 1.53, which puts it in group 6 of 6, group 1 being the genes least tolerant of losing a copy. Missense variants: 358 observed, 359.55 expected, observed/expected ratio (o/e) 1, 90% interval 0.91 to 1.09. Synonymous variants: 162 observed, 148.14 expected, observed/expected ratio (o/e) 1.09, 90% interval 0.96 to 1.25.
Homologues: Orthologues: chimpanzee MBLAC2 (99% identical), pig MBLAC2 (99% identical), rat Mblac2 (97% identical), mouse Mblac2 (97% identical), dog MBLAC2 (96% identical), guinea pig MBLAC2 (96% identical), rabbit MBLAC2 (86% identical), macaque MBLAC2 (81% identical), tropical clawed frog cetn3 (79% identical), zebrafish mblac2 (71% identical), Caenorhabditis elegans Y17G7B.3 (14% identical), Drosophila melanogaster tzn (14% identical). Paralogues in human: PNKD (18% identical), HAGHL (17% identical), ETHE1 (16% identical), HAGH (16% identical).
Diseases named in the same sentence as MBLAC2 in open-access papers:
MBLAC2 is named in the same sentence as 2 diseases in open-access papers, as found by Europe PMC text mining. Sharing a sentence is not in itself a finding about the gene and the disease. The quoted sentences say what the papers report.
colorectal cancer (1 paper, 2026). A primary or metastatic malignant neoplasm that affects the colon or rectum. "The depletion of EHMT2 or MBLAC2 sensitized colorectal cancer cells to ribosomal stress." (PMID 41851073, 2026).
cancer (1 paper, 2023). A tumor composed of atypical neoplastic, often pleomorphic cells that invade other tissues. "In support of this model, we find that CETN3, MBLAC2, and LYSMD3, core members of the POLR3G promoter hub, feature particularly high correlation z-scores across cancers." (PMID 37894362, 2023).